CENPA (centromere protein A)
Diseases named in the same sentence as CENPA in open-access papers (continued):
Sharing a sentence is not in itself a finding about the gene and the disease.
tumor (continued). "It has been reported that multiple genes such as CD56 polysialylation and CENPA had great impacts on tumor progression and metastasis via the Wnt/β-catenin signaling pathways in ccRCC." (PMID 39285496, 2024). "Subcutaneous tumour experiments were conducted on U251 cells after transfection with lentiviruses for CENPA knockdown and overexpression." (PMID 39620895, 2024). "We selected two anti-tumor drugs from two different databases that are positively correlated with high CENPA expression, including betulinic acid and GSK2126458." (PMID 39456925, 2024). "A similar trend was observed in tumor grade, where the expression levels of CENPA and TIMP1 were positively correlated with grade and that of MYCN was negatively correlated." (PMID 37213288, 2023). "Then we performed real-time quantitative PCR (qRT-PCR) and western blotting in 100 pairs HCC samples from Tongji hospital, and found that the mRNA and protein level of CENPA were up-regulated in tumor tissues compared to adjacent non-tumor tissues." (PMID 37928273, 2023). "Compared with normal tissues, CENPA expression in tumor tissues was elevated in all three cell types; TIMP1 was elevated in stromal cells and decreased in malignant cells; MYCN expression levels were not significantly different in different cell types." (PMID 37213288, 2023). "Results showed that compared with the control group, the tumor size and weight of the CENPA knockdown group were significantly reduced after subcutaneous injection." (PMID 37928273, 2023). "Although more evidence is needed to further support this new transcription complex, our study reveals the potential function of CENPA in tumor progression." (PMID 37928273, 2023). "CENPA expression in 289 tumor tissues was substantially higher than that in 32 normal tissues (P < 0.001), and it was also higher in 31 tumor tissues (P < 0.001)." (PMID 36163007, 2022). "The results of RT-qPCR and western blot analysis revealed that CENPA expression was increased in the tumor tissues relative to that in normal tissues." (PMID 35013138, 2022). "The analysis of data retrieved from TCGA TARGET GTEx database, GSE4290, and GSE16011 revealed a significant difference in the expression of CENPA between normal and tumor tissues, and the higher the grade, the higher the expression of CENPA." (PMID 36341103, 2022). "Second, the mechanisms by which CENPA regulates tumor cell stemness need to be investigated in more detail." (PMID 35816352, 2022). "Our results support that CENPA is a useful prognostic biomarker and tumor stemness regulator to help in LUAD prediction, disease management and therapy." (PMID 35816352, 2022). "A prior study found that tumor tissues exhibited a marked increase in CENPA mRNA compared to neighboring tissues." (PMID 36213834, 2022). "Six genes were up-regulated in the tumor group and high-risk group consisting of SMAD3, CENPA, KIF23, NUSAP1, INCENP, and SMC4." (PMID 36401386, 2022). "In HCC patients, increased CENPA mRNA was associated with elevated alpha-fetoprotein, advanced TNM stage, larger tumor size, advanced AJCC stage, and advanced pathology grade." (PMID 36213834, 2022). "Transcriptomically, CENPA was overexpressed in tumor tissues in the TCGA-KIRC project, GEO (gene expression omnibus) database and Oncomine database." (PMID 34627268, 2021). "In GSE14520, CENPA mRNA was significantly upregulated in tumor tissues compared to adjacent tissues (P < 0.0001)." (PMID 32337237, 2020). "When all microarray data of HCC patients in TCGA was included, CENPA mRNA was significantly overexpressed in tumor tissues compared with adjacent tissues (P < 0.0001)." (PMID 32337237, 2020).
tumor (continued). "Using integrated bioinformatic analysis, we evaluated the CENPA mRNA expression in tumor and adjacent tissues and correlated it with HCC survival and clinicopathological features." (PMID 32337237, 2020). "CENPA mRNA was significantly upregulated in tumor tissues compared with that in adjacent tissues, which were validated in The Cancer Genome Atlas (TCGA) and Gene Expression Omnibus (GEO) series (all P < 0.01)." (PMID 32337237, 2020). "The development of drugs that interfere with any cellular regulators of CENPA modification and function is something to consider for interfering with some aspects of tumour cell growth." (PMID 20119530, 2009). "Combining the results of the PPI network and correlation analysis, we inferred that IGF2BP3 may regulate CENPA protein levels, which in turn affects the transcription of downstream target genes and functions as a regulator of tumor progression." (PMID 41589308, 2025). "Conversely, the silencing of CENPA diminished glutamine metabolism and tumour progression." (PMID 41515893, 2025). "According to this study, HCC tissues had far higher levels of CENPA than nearby non-tumor tissues." (PMID 39968078, 2025). "Also, CENPA was found to correlate with the sensitivity of several anti-tumor drugs, including selumetinib, palbociclib, mim, tozasertib, bortezomib and other drugs." (PMID 40804263, 2025). "These values indicate favorable binding interactions, suggesting that both drugs could potentially inhibit CENPA activity or disrupt its function in tumor cells." (PMID 39456925, 2024). "The proportion of tumour cells entering the G2 and S phases decreased in the knockdown group, with most cells arrested in the G1 phase, indicating that CENPA might affect mitosis in the G1 phase." (PMID 39620895, 2024). "However, as time progressed, at 2 and 3 weeks, the tumour volume growth rate was slower in the CENPA knockdown group." (PMID 39620895, 2024). "TCGA and GETx data of PDAC patients indicated that CENPA is highly expressed in the tumor sample." (PMID 39456925, 2024). "The orthotopic xenograft tumor model showed that compared with the control group, CENPA knockdown significantly reduced the volume of orthotopic liver tumor, while the overexpression of CENPA had the opposite effect." (PMID 37928273, 2023). "In addition, immunohistochemical (IHC) staining in an independent cohort of 37 paired HCC samples indicated that expression of CENPA was increased in HCC tissues compared with the adjacent non-tumor tissues." (PMID 37928273, 2023). "Abnormal expression of CENPA may lead to chromosomal mismatches, disrupting genomic integrity and eventually promoting tumor development." (PMID 36341103, 2022). "In addition, it has been experimentally verified that CENPA has the ability to regulate tumor stemness." (PMID 35816352, 2022). "We then equally explored the effect of knockdown CENPA on the maintenance of tumor stemness." (PMID 35816352, 2022). "CENPA has been discovered to regulate the expression of key genes involved in cell proliferation, cell cycle, and centromere/kinetochore, and it also encourages tumor cell growth." (PMID 34976314, 2022). "As a result, abnormally high or low CENPA expression might disrupt genome integrity, resulting in chromosomal mis-polymerization and tumor occurrence." (PMID 36163007, 2022). "We found that CENPA expression within tumor tissue was higher than that in normal samples." (PMID 36163007, 2022). "Higher CENPA expression indicated shorter survival time and higher tumor grade and stage." (PMID 34627268, 2021). "Additionally, CENPA elevation was significantly correlated with advanced pathology grade, tumor stage, and poor survival in human epithelial ovarian cancer." (PMID 32337237, 2020). "The B3GAT3 and CENPA were all significantly upregulated in the tumor tissues." (PMID 33391344, 2020).
tumor (continued). "Aberrant PTMs on CENPA, including methylation and phosphorylation, impair CENPA deposition at centromeres and the recruitment of kinetochore components, leading to chromosome missegregation, which fuels tumor formation." (PMID 33167489, 2020). "Finally, targeting the regulation of expression of CENPA in tumour cells should allow the control of normal kinetochore assembly and proper cell division." (PMID 20119530, 2009). "In addition, CENPA may also affect cell division and tumor growth by interacting with other key cell cycle proteins." (PMID 40251374, 2025). "The object of this experiment is to test whether CENPA affects tumor growth in vivo." (PMID 35816352, 2022). "In HCC cells, the Kla modification of centromere protein A (CENPA) facilitates the formation of CENPA-YY1 complex, which activates the transcription of CCND2 and NRP2 genes, promoting tumor growth, metastasis, and angiogenesis in the TME." (PMID 41285721, 2025). "Given that IGF2BP3 is known to influence this microenvironment, we are analyzing prognostic models’ impact on KIRC immunity to assess the roles of IGF2BP3, CENPA, and MEF2B axis as a whole factor in tumor immunity." (PMID 41589308, 2025). "The lactylation of CENPA at the K124 site promotes CENPA activation and cooperates with Yin Yang-1 (YY1) to drive cyclin D1 and neuropilin two expressions, which in turn promotes tumor growth." (PMID 40584617, 2025). "Another study demonstrated that FOXM1 promotes tumor progression and glycolysis in TNBC by regulating CENPA gene expression." (PMID 40092695, 2025). "The carcinogenic potential of CENPA is greatly increased by lactylation at position K124, highlighting the critical role of this post-translational modification (PTM) in controlling tumor behavior." (PMID 39968078, 2025). "The expression levels of KIF2C, CENPA, CDC20, UBE2C, ESPL1, KIF23, and PLK1 were significantly higher in the tumor tissues of patients with a HOST-response compared to those without a HOST-response." (PMID 39201599, 2024). "A significant correlation was found between CENPA and TIMP1 expression in tumor tissues and immune cell infiltration, and as expression increased, most immune cell infiltration levels increased." (PMID 37213288, 2023). "The qRT-PCR results demonstrated that four cellular senescence-related genes (CENPA, CXCL8, EZH2, and G6PD) and two chemokine-related genes (CCL26 and CXCL5) were overexpressed in tumor tissues from HCC patients compared with paraneoplastic tissues." (PMID 36670201, 2023). "We also analyzed the correlation between CENPA expression and the HCC tumor stage and found the expression level of CENPA was positively correlated with the HCC tumor stage." (PMID 37928273, 2023). "We further validated the expression pattern of CENPA in GSE22058 and GSE14520 datasets and found that the expression level of CENPA in HCC was significantly higher than in adjacent non-tumor tissues." (PMID 37928273, 2023). "The methylation levels of CENPA and TIMP1 were downregulated in tumor tissues, while MYCN, in contrast to them, had elevated methylation levels." (PMID 37213288, 2023). "Wang and Shou have confirmed through detailed in vitro experiments that CENPA and TIMP1 are highly expressed in ccRCC tumor tissues and promote tumor progression through different mechanisms." (PMID 37213288, 2023). "The levels of glycometabolism-related hub genes (G6PD, CENPA, STC2, and PFKFB4) in tumor samples were higher than those in normal samples (p < 0.001)." (PMID 35938165, 2022).
tumor (continued). "The mean integral optical density (IOD/Area) values of CENPA and UCK2 were significantly upregulated in the tumor tissues (P < 0.0001)." (PMID 35359370, 2022). "TIMER tool further revealed expression of the 5 signature genes (ZNF695, CENPA, TROAP, BIRC5 and KIF20A) was strongly and positively correlated with high tumor purity but negatively influenced the infiltration of CD8+ T cells and macrophages." (PMID 33995639, 2021). "The most consistently upregulated genes across multiple tumor types were TOP2A (FC = 7.8), SPP1 (FC = 7.0) and CENPA (FC = 6.03), and the most consistently downregulated gene was ADH1B (FC = 0.15)." (PMID 33807717, 2021). "MGI is a gene expression assay, measuring the expression of five genes (BUB1B, CENPA, NEK2, RACGAP1, RRM2) related to histological grade and tumor progression, which recapitulates tumor grade and can predict the clinical outcome with high performance." (PMID 33287297, 2020). "Concurrently, tumor tissue and primary cultures displayed low transcript levels of proliferation-related genes, such as, TOP2A, ANKT, RAD51, UBE2C, CENPA, RRM2, and PLK." (PMID 15260889, 2004). "In addition, CENtromere Protein A-mediated centromere activation of cyclin E1/CDK2 in conjunction with FBXW7 deletion to induce chromosomal instability and tumor growth." (PMID 41373479, 2025). "Based on our experimental results, we observed an elevated expression of CENPA in tumor tissues, which showed a negative correlation with patient prognosis." (PMID 39456925, 2024). "In addition, we detected a decrease in CENPA lactylation level and downstream genes protein level (such as YY1, CCND1 and NRP2), in 2-DG treated HCC tumor tissues." (PMID 37928273, 2023). "Additionally, KEGG analysis showed that compared to CENPA or YY1 alone, these genes co-regulated by CENPA+YY1 are specially enriched in some tumor-related signaling pathway such as cell cycle and cellular senescence." (PMID 37928273, 2023). "Knockdown of CENPA inhibited HCC cell proliferation and tumor growth in vitro and in vivo." (PMID 37928273, 2023). "All these results suggested that CENPA promotes HCC cell proliferation and tumor growth." (PMID 37928273, 2023). "Thus, we demonstrated that CENPA interacts with YY1, forming the transcriptional complex, to co-regulate a set of genes involved in tumor progression." (PMID 37928273, 2023). "We only verified the tumor-promoting effect of CENPA through in silico and in vitro experiments without in vivo data." (PMID 34627268, 2021). "It was observed that CENPA expression levels were notably elevated in tumor tissues in comparison with their corresponding adjacent normal tissues." (PMID 34627268, 2021). "Of the top 12 transcriptional regulators, CENPA, FOXM1, and MYBL2 were among the most highly expressed and displayed the largest differences in expression between tumor and normal tissues; each was >8 times more highly expressed in LUAD as compared to normal lung." (PMID 32925947, 2020). "In addition, CENPA mRNA overexpression was correlated with AFP elevation, advanced TNM stage, and larger tumor size (all P < 0.05)." (PMID 32337237, 2020). "Additionally, CENPA mRNA were upregulated in HCC patients with alpha-fetoprotein (AFP) elevation, advanced TNM stage, larger tumor size, advanced AJCC stage, advanced pathology grade, and vascular invasion (all P < 0.05)." (PMID 32337237, 2020). "The results show that BIRC5, CENPA, KIF4A, DTYMK, PRC1, and TRIP13 have low beta values in tumor." (PMID 32391055, 2020). "Based on the key roles of CENPA and SFN in LIHC progression, future studies can further explore the molecular regulatory network of these two genes in LIHC pathogenesis, study their functions in the tumor microenvironment, and evaluate their application value in personalized treatment." (PMID 40251374, 2025).
tumor (continued). "For example, the regulation of CENPA could affect CCND1 and CDK4/6, interfering with cell cycle, and also affect the activity of the Wnt signalling pathway, ultimately affecting the proliferation and growth of tumour cells." (PMID 39620895, 2024). "In addition, overexpression of centromere protein A (CENPA), a regulator of metabolic reprogramming, may restore growth and glycolysis in tumor cells." (PMID 36339430, 2022).
CENPA also shares sentences with these, for which no sentence is quoted: gastric cancer (5 papers); glioblastoma (5); cervical carcinoma (4); colorectal tumors (4); head and neck cancer (4); CREST Syndrome (3); Fanconi anemia (3); Infertility (3); head and neck squamous cell carcinoma (2); lymphoma (2); thyroid carcinoma (2); triple-negative breast carcinoma (2); acute myeloid leukemia (1); adenocarcinoma (1); anal carcinoma (1); aneuploidy (1); basal cell carcinoma (1); borderline serous ovarian neoplasms (1); brain tumor (1); calcinosis (1); cervical squamous cell carcinoma (1); colorectal adenocarcinoma (1); colorectal gastrointestinal stromal tumor (1); diabetes (1); digestive system carcinoma (1); endocervical adenocarcinoma (1); esophagal carcinomas (1); esophageal cancer (1); hematological malignancies (1); infection (1).
A further 25 diseases each share a sentence with CENPA in 1 paper.